LGALS3 (galectin 3)
Diseases named in the same sentence as LGALS3 in open-access papers (continued):
Sharing a sentence is not in itself a finding about the gene and the disease.
tumor (continued). "In addition, the galectin-3-deficient mice produce lower levels of inflammatory cytokines in draining lymph nodes and, present structural and functional differences in the bone marrow and lymph nodes, that could be relevant in the dissemination of the tumor cells." (PMID 27526676, 2016). "We therefore suggest that the expression of sTn might be a mechanism to protect tumor cells from galectin-3 cell surface binding, thus preventing a cellular response to death-induced stimuli." (PMID 27835877, 2016). "In comparison to the control group (238 ± 42 tumor nodules per lung), the animals in the galectin-3-treated group showed significantly more metastatic nodules (437 ± 36 tumor nodules, p < 0.05) assessed by surface inspection after blind labelling using a dissecting microscope." (PMID 26160844, 2015). "Variable expression of galectin-3 was observed both in tumor cells and stromal cells." (PMID 26066796, 2015). "Interestingly, while weak tumor galectin-3 expression was correlated with increased invasion depth, positive expression was correlated with decreased tumor invasion (p = 0.012)." (PMID 26066796, 2015). "Thus, galectin-3 promotes tumor progression when expressed in the cytoplasm but shows antitumor activity when expressed in the nucleus." (PMID 25667921, 2015). "Notably, galectin-3 has been reported to regulate tumor cell metastasis and invasion by means of activating or expressing integrins." (PMID 25373317, 2015). "Our results suggest that strong galectin-3 expression is correlated with less tumor growth, while weak galectin-3 may be correlated with increased tumor growth." (PMID 26066796, 2015). "Furthermore, the simultaneous addition of 100 ng/ml recombinant galectin-3 to the co-culture systems partially restored the tumor-promoting effect of the senescent AD-MSCs." (PMID 26273429, 2015). "Tumor galectin-3 might have dual functions, as weak expression was correlated with increased tumor invasion, while positive expression was correlated with decreased invasion." (PMID 26066796, 2015). "The aim of our study was to identify whether galectin-1, galectin-3, and/or 90K/Mac-2BP correlates with tumor staging in patients with CRC and to investigate their possible clinical role in the prediction of patients with CRC." (PMID 26448934, 2015). "In the past decade, galectin-3 has been demonstrated to be widely expressed in tumor cells, and galectin-3 expression has been shown to be involved in various biological phenomena, including cell growth, adhesion, differentiation, apoptosis, cancer aggressiveness and metastasis." (PMID 25373317, 2015). "Galectin-3 was the most robustly expressed in tumor spheres during serial passages." (PMID 25669973, 2015). "Furthermore, the simultaneous addition of recombinant galectin-3 to the co-culture systems partially restored the tumor-promoting effect of the senescent AD-MSCs." (PMID 26273429, 2015). "The hypothesis of the present study is that extracellular galectin-3 may promote sphere formation in coordination with EGF or bFGF signaling in tumor sphere medium containing EGF or bFGF." (PMID 25669973, 2015). "Tumor hypoxia thus up-regulates the expression of galectin-3, which may in turn increase tumor aggressiveness." (PMID 26222311, 2015). "Changes in gene expression profiles for LGALS3 provide insights into stages of tumor progression." (PMID 25887408, 2015). "Nangia-Makker and co-workers hypothesized the involvement of galectin-3 secreted by tumor cells in angiogenesis." (PMID 24982845, 2014). "Additionally, Src kinase-dependent caveolin-1 (Cav1) phosphorylation increases focal adhesion turnover, RhoA activation, and tumor cell migration in a galectin-3-dependent manner." (PMID 24982845, 2014). "Additionally, in 44 paired primary HCC tissue samples, an increased mRNA level of galectin-3 was observed in most tumor tissues (28/44) compared with the corresponding adjacent non-tumor tissues, as evidenced by quantitative real-time PCR analyses (P = 0.039)." (PMID 25260879, 2014).
tumor (continued). "Decreased expression of galectin-3 in either compartment may lead to impaired tumor angiogenesis, as we have observed experimentally, as a result of diminished VEGF and/or resistance to TGFβ1." (PMID 24421272, 2014). "CXCR7 expression was further proved to regulate expression of vascular endothelial growth factor A and galectin-3, which may contribute to tumor angiogenesis and invasiveness." (PMID 25341042, 2014). "Finally, galectin-3 seems to play a relevant role in orchestrating distinct cell events in tumor microenvironment and for this reason, it can be considered a target in tumor therapies." (PMID 24982845, 2014). "Moreover, the potential downstream targets of CXCR7 are VEGFA and galectin-3, which are likely to participate in the regulation of tumor angiogenesis and contribute to the invasiveness of HCC cells." (PMID 25341042, 2014). "Hence, we report that galectin-3 disruption in tumor stroma and parenchyma decreases angiogenesis through interfering with the responses of macrophages to the interdependent VEGF and TGFβ1 signaling pathways." (PMID 24421272, 2014). "Moreover, when the galectin-3-expressing cell line (Tm1G3) was injected into KO animals, a delay in tumor growth was also observed comparing with its growth in WT animals." (PMID 24421272, 2014). "Principal Components Analysis (PCA) allowed for the discrimination of 2 experimental conditions in which expression of the tumor marker galectin-3 may play a significant role, namely exposure of cells to hypoxia under high glucose." (PMID 25221735, 2014). "Therefore we took great interest in identifying the relative galectin-1 and galectin-3 mRNA concentration by using tumor and non-tumor tissue from the same patient as reference." (PMID 24708743, 2014). "Interestingly, NK cells maturation and anti-tumor cytotoxic activity were increased in galectin-3 KO mice." (PMID 24982845, 2014). "We next injected the clones Tm1G3 or Tm1N3 into WT or KO mice to address whether the source of galectin-3 (tumor vs stromal origin) would impact on tumor engraftment and growth." (PMID 24421272, 2014). "Thus, Galectin-3 lattice formation provides another mechanism how altered glycosylation contributes to the malignant and invasive phenotype of tumor cells." (PMID 24592356, 2014). "We also discuss how cells at the tumor microenvironment may contribute to extracellular galectin-3 mediated tumor progression." (PMID 24982845, 2014). "In order to test the hypothesis that disruption of galectin-3 in either macrophages or tumor cells could affect VEGF secretion in response to TGFβ1 levels, we tested in vitro whether BMDM and/or cell lines secrete VEGF when cultured in TGFβ1-enriched medium." (PMID 24421272, 2014). "Indeed, galectin-3 is often overexpressed in various human solid tumors and blood malignancies and, in many cases, this altered expression correlates with the stage of tumor progression, suggesting an influence of this molecule in disease outcome." (PMID 24982845, 2014). "In parallel with the downregulation of galectin-3, malignant CMT displayed an overall loss of galectin-3-binding sites in the ECM and focal expression of galectin-3-binding sites mainly detected in intravascular tumor cells and endothelium." (PMID 24563633, 2014). "Meanwhile, increased galectin-3 expression in the tumor cells stimulates angiogenesis." (PMID 25260879, 2014). "Galectin-3, a member of the beta-galactoside-binding lectin family, is a multifunctional protein with various biological functions, including the proliferation and differentiation of tumor cells, angiogenesis, cancer progression, and metastasis." (PMID 25260879, 2014). "Furthermore, secreted 90K induced homotypic cell adhesion and the formation of multicellular aggregates of tumor cells by binding to galectin-3/Mac-2." (PMID 24156545, 2013).
tumor (continued). "Absence of galectin-3 from both tumoral and stromal compartments was associated with attenuated tumor growth, as compared to an experimental condition where both tumor and stromal cells expressed galectin-3." (PMID 24764473, 2013). "Galectin-3 also antagonises tumour cell apoptosis and anoikis." (PMID 23285151, 2012). "Moreover we tried to evaluate the correlations between galectin-3 and cyclin D1 expression in tumor tissue." (PMID 22024187, 2011). "Galectin-3 is a chemoattractant for monocytes and macrophages and expressed in tumor vascular endothelial cells and could function in the feed-back of stroma and cancer cells." (PMID 22039439, 2011). "Moreover, even if we focus on published data of CCRCC tumor patients the spectrum reaches from an increase in galectin-3 levels in tumors to reduced amounts of the lectin following tumorigenesis." (PMID 21958686, 2011). "In cancers, galectin-3 expression is dependent on the tumor histogenesis." (PMID 22216245, 2011). "Moreover they suggest that in tumours expressing and binding galectin-3, the distance between the tumour cells is of prognostic significance and an increase in the microvessel volume fraction points to a poorer survival rate." (PMID 22024187, 2011). "Tumour microenvironment elements were among the targets of the combination therapy since the relative frequency of COX-2 and galectin-3 positive cells and the microvascular density within the tumour mass were significantly reduced by treatment with WEB2170 or DTIC alone or in combination." (PMID 20465821, 2010). "The cell surface-expressed portion of LAMP1 maybe serve as a ligand for galectin 3, mediating cell-cell adhesion and indirectly tumor spread." (PMID 20831833, 2010). "Taking into account that we observed a slightly lower galectin-3 expression in metastasis appearing after a prolonged disease-free survival, we would argue that probably galectin-3 expression becomes upregulated during tumour progression, but to a minor degree." (PMID 17912244, 2007). "However, altered glycosylation in cancer can play an important role in tumour cell adhesion and migration, as well as in extravasation via interaction with galectin-3 on endothelial cells." (PMID 17912244, 2007). "Galectin-3 is also expressed in over 70% of colorectal primary tumours and liver metastasis." (PMID 17912244, 2007). "These purely synthetic galectin-3 compound inhibitors are shown to effectively inhibit galectin-3 binding to its ligands, galectin-3-mediated cancer cell activities in vitro and significantly reduce tumour growth and metastasis in vivo in chick embryos and in mice." (PMID 41023585, 2025). "Galectin-3 may promote tumorigenesis and metastasis through several mechanisms including induction of T cell apoptosis, inhibition of tumor cell apoptosis, promotion of angiogenesis, adhesion between tumor and endothelial cells, and promotion of tumor spread." (PMID 39759523, 2024). "Using a machine-learning recursive feature selection approach, we identified LGALS3 as the top gene that could classify a PDAC tumor as HypoxiaHI and confirmed the correlation between high hypoxia scores and LGALS3 expression in an additional cohort of PDAC RNA-seq data." (PMID 38510243, 2024). "LGALS3 regulated by SOX8/JUN complex was secreted by GSC into the tumour microenvironment, which could not only promote GBM MES transition by binding membrane protein ITGB1 on GSC in an autocrine form, but also promote immunosuppression by binding ITGB1 on TAM in a paracrine manner." (PMID 39629136, 2024). "Thus, the increased Galectin-3 levels detected in OC ascites may be a result of increased production in tumor cells as well as increased inflammation in the peritoneum." (PMID 39759523, 2024). "Moreover, our current discoveries suggest that LGALS3 may play a pivotal role in promoting hepatocarcinogenesis and malignant progression by enhancing tumor immune cell infiltration and upregulating immune checkpoint expression." (PMID 38643145, 2024).
tumor (continued). "Therefore, we asked whether the expression and release of galectin-3 is a common tumor escape mechanism of different tumor cells." (PMID 38259448, 2023). "However, it was unclear whether this in vivo effect was galectin-3-dependent, and if so, whether the therapeutic effect resulted from the interaction of the peptide with human galectin-3 or mouse galectin-3 secreted by the host in the tumor microenvironment." (PMID 37753083, 2023). "It was suggested that galectin-3 could promote tumor metastasis mostly in an Akt-dependent way." (PMID 37345016, 2023). "Besides MHC-II, other ligands of LAG-3 include galectin-3 found on tumor and tumor stromal cells, liver sinusoidal endothelial cell lectin (LSECtin) which is expressed on liver and melanoma cells, and fibrogen-like protein 1 (FGL1) secreted from hepatocytes and tumor cells." (PMID 37304291, 2023). "In addition, LGALS3 expression positively correlated with tumor grade." (PMID 36745330, 2023). "The circulating galectin-3 concentration in the serum of cancer patients has been reported to be higher than that of healthy individuals, and the level of galectin-3, which can vary across different human tumors, has been shown to correlate with tumor progression." (PMID 36914828, 2023). "Moreover, localization of the Galectin-3 seems to vary during tumor stage evolution." (PMID 36936148, 2023). "Indeed, MCP could inhibit cell adhesion in galectin-3-overexpressing tumor cells, reducing tumor cell aggregation and adhesion to the endothelial cells, thereby inhibiting the metastatic potential of cancer cells." (PMID 36873388, 2023). "Therefore, galectin-3 is regarded as an intrinsic tumor escape mechanism." (PMID 38259448, 2023). "In addition, it has been reported that galectin-3 could promote tumor metastasis primarily in AKT-dependent signaling pathways and could act as a crucial regulator in the development and metastasis of many cancers." (PMID 37685842, 2023). "The increased expression of galectin-3 detected after AF16 and TMZ treatment could be explained by the cytotoxic effect of this therapy causing membrane damage and increased autophagy as part of regulated death of tumor cells and senescent immune cells." (PMID 35301393, 2022). "However, inhibition of galectin-3 also impacts the tumor stroma cells." (PMID 36703969, 2022). "Similarly, galectin-3 protects different tumor types from apoptosis triggered by different stimuli." (PMID 35008740, 2021). "Similarly, platelet GPVI may also contribute to metastasis processes, as it has been shown to bind galectin-3 on tumor cells." (PMID 34360659, 2021). "Indeed, the CD8+ TILs that bind galectin-3 in the tumor microenvironment co-express LAG-3 and PD-1." (PMID 34572756, 2021). "Hence, the function of Galectin-3 and Galectin-9 and their correlation with tumor prognosis remain largely unknown." (PMID 32995093, 2020). "The correlation between LGALS3 expression and the infiltration of multiple intra-tumoral immune cell types, including B cells (CD20), T cells (CD4 and CD8), macrophages (CD68), and M2 tumor-associated macrophages (CD163), was evaluated by Spearman correlation analysis." (PMID 32528967, 2020). "Also, our speculation indirectly supported the phenomenon of Galectin-3 promoting tumour cell metastasis in our study as well as other literatures." (PMID 32801345, 2020). "Our results suggest that Galectin-3 downregulation in tumors during the course of cancer progression, invasion, and further metastasis is intrinsically associated with ECM remodeling, which favors Gal-3-mediated detachment of tumor cells to the primary site via regulation of GAGs." (PMID 31949431, 2019). "Thus, given their ability to regulate both β1 and β3 integrin function, dysregulation of galectin-1 and galectin-3 expression in the tumor microenvironment may have a profound impact on the efficacy of therapies targeting RTKs." (PMID 31109009, 2019).
tumor (continued). "Besides that, the interaction between T antigen and galectin-3 influences adhesion of tumor cells to the endothelium, which could promote metastasis." (PMID 31355147, 2019). "Intracellular galectin-3 is involved in regulation of proliferation, differentiation, survival and apoptotic events, while extracellular galectin-3 affects numerous biological processes including cell adhesion and tumor invasion, immune cell activation, and angiogenesis." (PMID 30765738, 2019). "In this capacity, galectin 3 may facilitate tumour progression driven by macrophages." (PMID 29666124, 2018). "In tumours, mainly the intracellular functions of Gal-1 have been linked to pro-tumourigenic process, as Gal-1 can interact with oncogenic H-RAS to promote angiogenesis, while Galectin 3 (Gal-3) and K-RAS proteins are found to team up in an unholy alliance in cancer cells." (PMID 29498681, 2018). "Despite the fact that T cells might also produce galectin-3, elimination of tumor-derived galectin-3 resulted in improved expansion of tumor-reactive T cells, indicating an important role for the galectin-3 produced by the tumor in the suppression of T cell activation." (PMID 28401257, 2017). "Several galectin-3 pro-tumor effects may coexist in human tumors." (PMID 28986561, 2017). "The soluble factor galectin-3 might play a role by tumor-induced suppression of T cell activation." (PMID 28401257, 2017). "The positive ezrin and galectin-3 protein expressions in poorly differentiated patients were significantly higher than in the well-differentiated patients (all P<0.05), but were not correlated with age, menopausal status, histological type or tumor size (all P>0.05)." (PMID 28355349, 2017). "In addition, we also explored the mechanisms by which Galectin-3 regulated tumor cell migration." (PMID 29254179, 2017). "Firstly, we hope to prove that if Galectin-3 loses its N-terminal collagen domain and then could not form pentamer, it may loss its ability of promoting tumour procession, even inhibit cell growth and motility." (PMID 28701735, 2017). "Finally, we knocked out galectin-3 from a tumor cell line using CRISPR/Cas9 technology." (PMID 28401257, 2017). "Besides altered glycosylation, galectin-3 expression is commonly dysregulated within the tumor microenvironment, either by altered expression in tumor cells or by its expression in infiltrating leukocytes [for a comprehensive list of studies in human tumors, see Ref." (PMID 27242966, 2016). "Moreover, the subcellular distribution of galectin-3 varies among different tumor types." (PMID 27435226, 2016). "Therefore, in our study, galectin-3 expression by tumor cells may have enhanced the survival of disseminating tumor cells in the circulation." (PMID 27526676, 2016). "Galectin-1 and galectin-3 could contribute to tumour immunosuppression." (PMID 27447355, 2016). "However, galectin-3 is generated not only by tumor, but also by peri tumoral inflammatory and stromal cells, indicating that the tumor behavior could be influenced by both: tumor and microenvironment." (PMID 27526676, 2016). "Our finding that Lgals3 was up-regulated at the mRNA level in neoplastic relative to preneoplastic cell lines is in good agreement with accumulating evidence indicating that galectin-3 is closely involved in tumor cell transformation, migration, invasion and metastasis for a number of cancers." (PMID 27129173, 2016). "As galectin-3 can also act on tumor-infiltrating T cells to impair their anti-tumor function, it is possible that these chemically-modified heparin derivatives could possess additional anti-tumor effects in cancer patients as a result of inhibition of galectin-3-mediated T cell apoptosis." (PMID 26160844, 2015). "Tumor galectin-3 expression may be necessary for a differentiated phenotype and ECM adhesion." (PMID 26066796, 2015).